HOTAIR (HOX transcript antisense RNA)
Diseases named in the same sentence as HOTAIR in open-access papers (continued):
Sharing a sentence is not in itself a finding about the gene and the disease.
cancer (continued). "Specifically, it has been shown in several cancer cell lines that osteopontin, a secreted protein whose expression has been coupled to tumor progression and metastasis, induces HOTAIR expression inhibiting the expression of IRF1 via PI3K/AKT pathway." (PMID 37308974, 2023). "HOTAIR is also known as an oncogene, with its expression strongly correlated with the grade and prognosis of a variety of cancers." (PMID 36997931, 2023). "LncRNAs have been shown to be expressed in all major cancer types, contribute to the hallmarks of cancer, and can act as oncogenes (“onco-lncRNAs”, such as HOTAIR, NEAT1 and MALAT1) or tumor suppressors (e.g. GAS5, MEG3, NBAT and LINC-PINT)." (PMID 37346034, 2023). "The overexpression of HOTAIR is positively correlated with poor prognosis and tumor recurrence in a variety of cancers." (PMID 37576402, 2023). "With the increased regulation of HOTAIR, the cell cycle progresses, cell proliferation is ensured, and apoptosis of cancer cells is inhibited." (PMID 38813489, 2023). "Its genetic variations increase intronic activity and enhance HOTAIR expression in specific cancer cells." (PMID 37776415, 2023). "Prior investigations have linked polymorphisms in the HOTAIR and THRIL genes polymorphisms to various diseases, including rheumatoid arthritis, cancers, preeclampsia (PE) and others." (PMID 38087305, 2023). "It was also involved in epithelial-mesenchymal transformation (EMT) in normal tissue and tumors, and lncRNA HOTAIR has potential for cancer targeted therapy." (PMID 38070058, 2023). "HOTAIR plays a pivotal role in the pathogenesis of several cancers, the ectopic expression of which is involved in drug resistance, enhancing cell viability and metastasis through various signaling pathways in tumors." (PMID 37880710, 2023). "The lncHUB2-predicted biological functions for HOTAIR recover many of these recently established functions including HOTAIR’s involvement in cancer, cell cycle, DNA damage response and immune signaling." (PMID 36869839, 2023). "This prevents the downstream effects of HOTAIR on gene regulation, chromatin remodeling, and cancer progression." (PMID 36997931, 2023). "The upregulation of HOTAIR in normal breast epithelial cells was shown to induce hallmarks of cancer such as increased proliferation, migration and tumor invasion in vivo." (PMID 36869839, 2023). "During the past years, a number of evidences have demonstrated that HOTAIR function as an important regulator in the development and metastasis of many types of cancer." (PMID 37621132, 2023). "At the same time, we also conducted overexpression experiments in both cells to further illustrate the role of HOTAIR with different degrees of cancer." (PMID 37576402, 2023). "For example, the lncRNA HOTAIR (HOX Transcript Antisense Intergenic RNA) has been found to be overexpressed in several types of cancer and promotes metastasis by interacting with chromatin-modifying enzymes and promoting epigenetic changes." (PMID 37627188, 2023). "It confers resistance to chemotherapy and targeted therapies by regulating the genes that control drug metabolism, DNA repair, and apoptosis, highlighting the potential of targeting HOTAIR as a strategy to overcome drug resistance in cancer." (PMID 36997931, 2023). "In conclusion, there is increasing evidence that HOTAIR acts as an oncogene in various cancers and that its up-regulation can lead to malignant transformation and tumorigenesis." (PMID 36924407, 2023). "We explored the relationship between lncRNA HOTAIR and three important molecules, TGF-β1 and ZEB1 and E-cadherin, which are associated with cancer progression, metastasis and epithelial-mesenchymal transformation (EMT)." (PMID 38070058, 2023).
cancer (continued). "It was postulated that the overexpression of HOX antisense intergenic RNA (HOTAIR) is important for many types of cancers." (PMID 38813489, 2023). "HOTAIR, like in many cancers, is significantly overexpressed in leukemic compared to healthy haemopoietic cells." (PMID 37267628, 2023). "High HOTAIR level in cancer cells will inhibit the function of certain tumor metastasis suppressor genes and promote tumor deterioration, conversely, silencing HOTAIR will result in cancer cells lose their ability to metastasize." (PMID 36810034, 2023). "HOTAIR is mostly studied in cancer models where its overexpression promotes cell migration and metastasis by altering gene expression." (PMID 36115964, 2022). "Evidence revealed that lncRNA HOTAIR plays an essential role in tumorigenesis and progression in human cancers." (PMID 36438563, 2022). "We found that HOTAIR was upregulated in OS, promoting the proliferation and migration of cancer cells and activating the PI3K/AKT pathway." (PMID 35435107, 2022). "We first assessed HOTAIR expression level in ASCs versus cancer cell lines where HOTAIR function has been previously studied." (PMID 36115964, 2022). "HOTAIR is upregulated in epithelial cancer cells, inducing histone methylation and cancer cell invasion." (PMID 36699052, 2022). "Direct or indirect suppression of the WNT pathway was also reported to downregulate HOTAIR expression in cancer cells." (PMID 36579891, 2022). "More research is needed to further understand the role of HOTAIR in the pathogenesis of human cancers." (PMID 36100611, 2022). "Collectively, these studies indicate that HOTAIR level increases in human cancer and is related to metastasis and poor prognosis." (PMID 35619625, 2022). "Further studies revealed that interference with miR-6888-3p promotes the proliferation and migration of cancer cells and reverses the effect of HOTAIR knockdown on cell function." (PMID 35435107, 2022). "For instance, the oncogenic properties of HOTAIR and its correlation to poor prognosis in various cancers has been well documented." (PMID 35788171, 2022). "Recently, the critical role of HOTAIR in cancer development has been well investigated and a large body of evidence demonstrates that HOTAIR is elevated in cancer and correlates with metastasis and poor prognosis." (PMID 35798695, 2022). "We observed that cellular invasion decreased after HOTAIR overexpressing cells underwent complete Dox withdrawal, suggesting that ongoing HOTAIR is required to promote increased cancer cell metastasis." (PMID 36579891, 2022). "Among all the cancer associated long non-coding genes reported (, Lnc2Cancer v3.0), we identified mutations of MALAT1, HOTAIR and ZFAS1 in these cell line models." (PMID 36153537, 2022). "As a result, an increase in HOTAIR (seen in various types of cancer) results in increased PD-L1, explaining HOTAIR’s oncogenic nature." (PMID 36612180, 2022). "Forced overexpression of HOTAIR promotes, whereas constitutive knockdown of HOTAIR reduces, cell proliferation in cancer cells." (PMID 36471329, 2022). "Similar to previous studies, transgenic overexpression of HOTAIR mediated increased cancer growth and invasion of MDA-MB-231 cells." (PMID 36441764, 2022). "This study is the first to show that HOTAIR rs7958904 was associated with HCC susceptibility, although it has been reported to be associated with the risk of other cancers." (PMID 36418931, 2022). "Although some of the lncRNAs, such as HOTAIR, have been extensively investigated as oncogenic drivers in multiple cancer types, we are still far from understanding the major common oncogenic pathways by which they induce neoplastic transformation." (PMID 36230680, 2022).
cancer (continued). "Knockdown of HOTAIR, a lncRNA frequently overexpressed in various carcinomas and potential anti-cancer target, was shown to decrease miR-125a-5p and increase caspase-2 cleavage resulting in apoptotic death." (PMID 36171196, 2022). "The p-PI3K/p-AKT/MMP-2/9 signaling pathway is closely related to cancer cell migration, invasion and metastasis, and miR-217-5p inhibitors can restore the effect of HOTAIR silencing on HCC cells by activating this pathway." (PMID 35093153, 2022). "For example, lncRNA HOTAIR promotes tumor metastasis in almost all types of cancers by reprogramming chromatin state." (PMID 35475470, 2022). "Based on previous reports and our analysis results, it has been discovered that HOTAIR plays an important role in the occurrence and development of various cancers." (PMID 36115953, 2022). "Other studies have demonstrated that HOTAIR promotes cancer cell proliferation by activating the PI3K/AKT/mTOR signaling pathway, suggesting that GEN exerts its anticancer effects by downregulating HOTAIR through inhibition of this signaling pathway." (PMID 36552560, 2022). "TCGA indicated that HOTAIR and Suv39H1 were highly expressed in the patients with different cancer subclasses/different nodal metastasis status/individual cancer stages (p < 0.05, vs Normal breast tissues by ANOVA)." (PMID 35619625, 2022). "The HOX transcript antisense RNA (HOTAIR) gene is highly expressed in a variety of cancers, and deletion of HOTAIR can inhibit the aggressiveness of cancers." (PMID 35860595, 2022). "Although these studies disclosed the function of HOTAIR in cancer, the effect of HOTAIR on hypoxia-induced chemoresistance remains poorly understood." (PMID 35798695, 2022). "Several studies indicate that HOTAIR takes part in the regulation of EMT in cancer cells, affecting chemotherapy resistance." (PMID 36100611, 2022). "For example, lncRNA HOTAIR shows similar functions in regulating cancer cell behaviors in different types of cancer." (PMID 35287551, 2022). "In recent years, three lncRNAs located by the five positive association SNPs found in this study, namely HOTAIR, PVT1 and EGFR-AS1, have been reported to be involved in the occurrence and development of a variety of cancers through the ceRNA mechanism." (PMID 36418931, 2022). "HOTAIR is overexpressed in a wide range of human cancers and correlated with tumor progression and poor prognosis." (PMID 36471329, 2022). "HOTAIR, an oncogenic long non-coding RNA (lncRNA), promotes cancer progression in different cancers." (PMID 36471329, 2022). "HOTAIR, which is likewise found on chromosome 12q13.13 and is an oncogenic lncRNA in a variety of cancers, is an antisense transcript of HOXC11." (PMID 36031658, 2022). "HOTAIR enhances the self-renewal ability of CSCs and plays a vital role in cancer chemosensitivity and recurrence." (PMID 36100611, 2022). "The HOTAIR gene has a major effect on cellular homeostasis and plays a critical role in many types of cancers." (PMID 36361470, 2022). "Molecular mechanisms of HOTAIR in cancer progression include recruitment of lysine specific demethylase 1 (LSD1) complexes and PRC2, histone 3 lysine 4 (H3K4) demethylation and histone 3 lysine 27 (H3K27) methylation." (PMID 35359573, 2022). "Plasma levels of H19 in breast cancer, and H19, HOTAIR, and MALAT1 in gastric cancer have shown high diagnostic potential, while single nucleotide polymorphisms in the H19 gene have applications in cancer risk prediction." (PMID 35892331, 2022). "lncRNA HOTAIR is one of the broadly studied ncRNAs HOTAIR is an important EMT regulator and has been implicated in the pathogenesis of several cancers." (PMID 35755302, 2022). "As such, targeting HOTAIR overexpression is of clinical interest as a potential therapy for cancer patients." (PMID 36579891, 2022). "HOTAIR (ranked third), is related to the progression of various cancers; however, its functions in AS are still unclear." (PMID 35495166, 2022).
cancer (continued). "The exact molecular mechanisms by which HOTAIR is involved in cancer progression are more intricate than originally thought and have not yet been applied in the clinic." (PMID 36100611, 2022). "For instance, HOTAIR is overexpressed in various cancers and correlates with the metastasis and invasion of these cancers." (PMID 35757472, 2022). "This specific site, bound by YTHDC1, is critical for promoting HOTAIR-dependent cancer phenotypes and gene expression in TNBC cells." (PMID 36441764, 2022). "In cancer cell lines, HOTAIR has been reported to scaffold for chromatin regulators with broad effects on gene expression." (PMID 36115964, 2022). "We found that high HOTAIR levels were only significantly associated with decreased survival in the context of high YTHDC1 mRNA, suggestive of a role for YTHDC1 in enhancing HOTAIR’s ability to mediate more aggressive cancer." (PMID 36441764, 2022). "HOTAIR, a well-studied LncRNA, for example, influences cancer growth and metastasis in a variety of cancer types." (PMID 36120580, 2022). "LncRNA HOTAIR has recently emerged as a promoter of metastasis in various cancer types, including GC, through the EMT process." (PMID 34923813, 2022). "We find that HOTAIR expression level in ASCs from two unrelated donors is higher or comparable to that of cancer cell lines, confirming the relevance of primary ASCs as a model system to assess the relative abundance of HOTAIR isoforms." (PMID 36115964, 2022). "Recently, a series of studies revealed that HOTAIR plays a vital role in autophagy-mediated chemotherapeutic sensitivity in human cancers." (PMID 36100611, 2022). "The expression of HOTAIR in the sera of cancer patients was increased, which was correlated with invasion, lymphatic node metastasis, advanced tumor stages, tumor recurrence and short OS." (PMID 36438563, 2022). "How HOTAIR specifically accomplishes initial transcriptional repression at its target loci, and how other pathways and cancer contexts influence HOTAIR function, remain elusive." (PMID 36441764, 2022). "In many previous studies, lncRNA HOTAIR has been proved to be a pro-cancer factor to mediate cancer malignant progression, including breast cancer, hepatocellular carcinoma and gastric cancer." (PMID 35193668, 2022). "HOTAIR expression in these cell models allows cancer stem cells to self-renew and thus maintain constant populations throughout cell divisions." (PMID 35954194, 2022). "Our data imply that the presence of HOTAIR transcript is required to promote cancer metastasis and propagate changes in the chromatin landscape." (PMID 36579891, 2022). "Although HOTAIR is differentially expressed in various cancers, most lncRNA expression is histologically specific." (PMID 36389111, 2022). "CCL18 facilitated cancer development by upregulating HOTAIR expression, providing a potential new therapeutic target for cancer diagnosis and treatment." (PMID 35222443, 2022). "In order to study the function of HOTAIR in BCSCs, we first prepared to isolate the corresponding cancer stem cells from MCF-7 and MDA-MB-453." (PMID 36273585, 2022). "HOTAIR is a well-established pro-oncogenic lncRNA which has been attributed a variety of functions in cancer and native contexts." (PMID 36115964, 2022). "HOTAIR was reported to be frequently upregulated in various types of cancer, including breast cancer, esophageal cancer, lung cancer, gastric cancer, and melanoma." (PMID 33450825, 2021). "For example, lncRNA HOX antisense intergenic RNA (HOTAIR) is involved in cancer cell proliferation, apoptosis, invasion, and metastasis, and its increased expression in the blood is associated with a high mortality rate." (PMID 34778084, 2021). "Several lncRNAs identified in other malignant tumors, such as HOTAIR, CCDC26, and AOC4P, have also been evaluated in GISTs and were shown to be associated with GIST metastasis and sensitivity to imatinib." (PMID 34218261, 2021).
cancer (continued). "We first analyzed, by ddPCR expression of several cancer-associated lncRNAs (MALAT1, NEAT1, HOTAIR, H19, PVT1, MEG3) in both FNAs and surgical specimens and selected MALAT1, HOTAIR, and PVT1 as cancer biomarkers." (PMID 33030666, 2021). "It has also been reported that the HOTAIR, influences the development of cancer invasion via immune responses." (PMID 34805277, 2021). "Enforced expression of HOTAIR in epithelial cancer cells increases cancer invasiveness and metastasis through reshaping epigenome, resembling embryonic fibroblasts in a manner dependent on PRC2." (PMID 33667269, 2021). "According to the analysis, these miRNAs targeted pathways such as cellular development, HOTAIR regulatory pathway, cancer drug resistance pathway, TH1, and TH2 activation pathway, and apoptosis pathway as well." (PMID 35052749, 2021). "HOTAIR is an oncogenic lncRNA, and numerous studies have determined that HOTAIR is highly upregulated in a wide variety of human cancers." (PMID 34367966, 2021). "The aim of this review is to highlight the role of HOTAIR in rare cancers, proposing it as a new biomarker usable in the management of these tumors." (PMID 34576322, 2021). "When HOTAIR was knocked down, the proliferation, invasion, and migration ability of cancer cells were inhibited." (PMID 34207450, 2021). "We utilized a lncRNA array dataset (GSE81034) to analyze the expression of well-known, cancer metastasis-associated lncRNAs (i.e., MALAT-1, NEAT-1, HOTAIR, and HOXA11-AS) in the five cell lines by comparing exosomal RNA versus total RNA." (PMID 33514011, 2021). "In general, HOTAIR has been shown to recruits chromatin-modifying proteins and to affect cancer epigenome modulation." (PMID 34320988, 2021). "HOTAIR regulates the proliferation and metastasis of cancer cells, and for many tumor types, it has been found to be predictive of patient prognosis and progression." (PMID 34266873, 2021). "Subsequent studies elucidated the correlation between HOTAIR deregulation and cancer progression in 26 human tumor types." (PMID 33422052, 2021). "Based on higher co-expression in malignant (n = 11) but not in benign (n = 8) nodules after surgery, MALAT1, PVT1 and HOTAIR were selected as putative cancer biomarkers to analyze 135 FNA samples." (PMID 33030666, 2021). "For example, upregulated expressions of NEAT1 and HOTAIR are responsible for therapeutic resistance in BC, OC, and various other cancer cells to chemotherapy, e.g., paclitaxel, 5-FU, cisplatin, tamoxifen, radio and endocrine therapies." (PMID 34885213, 2021). "HOTAIR is a lncRNA overexpressed in a variety of cancer cells, including lung cancer, hepatocellular carcinoma, and colorectal cancer." (PMID 34199840, 2021). "Taking together, our results suggest that HOTAIR is able to regulate the proliferation of cancer cells by modulating YBX1 nuclear localization, promoting in turn PCK2 and PDGFRB expression." (PMID 34266873, 2021). "Elevated HOTAIR expression is constantly observed in many malignancies and is closely related to cancer development." (PMID 34073224, 2021). "In a recent study, osteopontin was reported to regulate lncRNA HOX transcript antisense RNA (HOTAIR) expression in cancer cells, suggesting the potential involvement of the interaction between osteopontin and HOTAIR in cancer." (PMID 33446111, 2021). "HOTAIR is a crucial modulator of cancer stem cells (CSCs), able to induce proliferation, colony formation, migration, and self-renewal capacity." (PMID 33540611, 2021). "HOTAIR plays an essential role in inducing malignancy, invasion, and proliferation in various cancers, and in contrast, miR-141 in a sequence-specific manner can suppress malignancy in human cancer cells by inhibiting HOTAIR." (PMID 33805687, 2021). "Future experiments aimed at validating these interactions and exploring their implications for cell functionality will serve to better elucidate the myriad roles played by HOTAIR in regulating cell biology and cancer development." (PMID 34266873, 2021).